CDKN2C (cyclin dependent kinase inhibitor 2C)
Diseases named in the same sentence as CDKN2C in open-access papers (continued):
Sharing a sentence is not in itself a finding about the gene and the disease.
tumor (continued). "In addition, some reports propose the contribution of CDKN2C as tumour suppressor gene in different neoplasms." (PMID 36334246, 2023). "Moreover, CDKN2C expression was significantly higher in tumor tissues from HBV-derived HCC compared to adjacent tissue." (PMID 32483149, 2020). "Furthermore, PRP induced the up-regulation of cyclin-dependent kinase inhibitors genes (CDKN2A; CDKN2, 2 and CDKN2C) which are considered important tumour suppressor genes." (PMID 31388092, 2019). "Cdkn2c+/− mice develop tumours consistent with acromegaly/gigantism, due to GH secreting tumours." (PMID 26320859, 2016). "This hypothesis is supported by the presence of the cyclin-dependent kinase inhibitor 2B (CDKN2B) and 2C (CDKN2C) tumor suppressor genes in the identified gene set." (PMID 23049694, 2012). "Given that Cdkn2c is a known tumor-suppressor gene that regulates cell proliferation, the decreased proliferation observed in inner ear progenitor cells following Bmi1 knockout might be attributed to the increased expression of p18INK4c due to the decrease in H3K27me3 levels." (PMID 41257804, 2025). "In our case, the tumor specimen presented heterozygous deletions of CDKN2A, CDKN2B and CDKN2C, and gains of CDK6 and CCND2." (PMID 38369555, 2024). "MLL binds to the promoter regions of cyclin-dependent kinase inhibitors (CDKis) p18Ink4c (CDKN2C) and p27Kip1 (CDKN1B), maintaining the expression of these genes and inhibiting tumour formation." (PMID 34439335, 2021). "There are a further eight tumor-suppressor genes (DLEU2, CDKN2C, SPRY4, UBE2QL1, LIN9, TFPI2, LRIG3, DUSP1) and six genes serve as both oncogenes and tumor-suppressor genes (FOXO1, CAV1, KLF6, CDK6, PLK1, CTGF)." (PMID 30563222, 2018). "Our model is able to reject local fragility for 13 of the 15 peaks containing known tumour suppressors, VHL/FANCD2 and CDKN2C being the exceptions." (PMID 29089486, 2017). "Among the MNA tumors (n=10), five tumor suppressor genes (among other genes) were underexpressed within the distal 1p: CAMTA1, KIF1B, PRDM2, FABP3, and CDKN2C; whereas MYCNOS and MYCN were the two top differentially upregulated genes on 2p." (PMID 23656755, 2013). "It has been recently argued that CDKN2C and PTEN partner in tumor suppression by constraining a positive regulatory loop between cell growth and cell cycle control pathways." (PMID 20805891, 2010). "For somatic copy number alterations, cases with high PLK3 expression not only demonstrated significant amplification peaks for PIK3C2B, PDGFRA, EGFR, and CDK4, which are defined as oncogenic drivers, but they also showed deletion peaks for tumor-suppressor genes, such as CDKN2A and CDKN2C." (PMID 39866232, 2025). "Age did not impact the effects of inactivation of Stag2, Setd2, Cdkn2c and Rbm10 in either context, further suggesting that age interacts with specific tumor suppressor pathways as opposed to generically weakening the effects of driver mutations." (PMID 41188600, 2025). "Interestingly, genes encoding CDK inhibitors, such as CDKN1A (p21Cip1), CDKN2A (p16INK4A), CDKN2C (p18INK4C) were downregulated in our CNFPA, which is consistent with a cyclin-mediated oncogenic mechanism, whereby these proteins act as tumor suppressors." (PMID 35260162, 2022). "INK4 expression accurately distinguished tumor from normal tissue, particularly CDKN2A and CDKN2C." (PMID 35771229, 2022). "Along with CDKN2A, other INK4 family members, CDKN2B, CDKN2C, and CDKN2D, also showed a good ability to distinguish tumor from normal tissue, particularly CDKN2C, suggesting that they can be used as biomarkers for the screening, diagnosis, and prognosis prediction of HCC." (PMID 35771229, 2022).
tumor (continued). "For other known tumour suppressor loci, CDKN2C and FANCD2/VHL, our model could not identify this signature." (PMID 29089486, 2017).
cancer (51 papers, 2005 to 2025). A tumor composed of atypical neoplastic, often pleomorphic cells that invade other tissues. "The mutations of CDKN2C can be observed in 13 cancers (GBM, etc.), and missense mutation was predominant." (PMID 35751045, 2022). "Collectively, the relationship between CDKN2C expression and patient prognosis may be complex, but an increased CDKN2C expression level was a prognosis risk signal for most cancers." (PMID 35751045, 2022). "CDKN2C is frequently functionally inactivated in multiple malignancies; for instance, pan-cancer analyses have described decreased expression or deletion in diverse tumors." (PMID 41226058, 2025). "In our study, we identified six signature genes, namely TNFRSF11B, METTL7B, SSTR2, OXTR, CDKN2C, and H19 which have been extensively studied in the past and are known to play a significant role in cancer." (PMID 37713112, 2024). "In human cancers, CDKN2C gene deletion or significantly lower mRNA expression is present only in less than 1% of cancers, almost uniquely in low- and high-grade gliomas." (PMID 38561743, 2024). "The indicated CDKN2C was reported to be correlated to carcinomas, especially thyroid-related disorders." (PMID 36906575, 2023). "Second, we failed to collect body fluid samples to verify the potential of CDKN2C expression levels in differentiating cancer tissue from non-cancer tissue." (PMID 35751045, 2022). "For the pan-cancer analysis, CDKN2C expression represents a poor prognosis in seven cancers (LGG, etc.), while the gene is related to a favorable prognosis for CESC and THYM." (PMID 35751045, 2022). "AUC values (all > 0.8) of CDKN2C expression in eight of the 20 cancers indicated the conspicuous ability of CDKN2C in distinguishing the eight cancer tissues from the control tissues." (PMID 35751045, 2022). "The suppressing effects of CDKN2C expression have been identified in numerous cancers due to its typical function." (PMID 35751045, 2022). "CDKN2C was identified to participate in the occurrence and/or development of and play essential roles in multiple cancers such as esophageal squamous cell carcinoma, liver hepatocellular carcinoma (LIHC), and lung adenocarcinoma (LUAD)." (PMID 35751045, 2022). "Unfortunately, among the eight cancers where CDKN2C shows the independent prognostic effects, except for LGG and LIHC, no prognosis and corresponding mechanism research are available for reference." (PMID 35751045, 2022). "Taken together, the comprehensive molecular mechanisms of CDKN2C expression in cancers are complex and need further study." (PMID 35751045, 2022). "The pan-cancer analysis of CDKN2C expression further demonstrated its prognostic and differentiation effects in multiple cancers." (PMID 35751045, 2022). "In the three cancers, CDKN2C expression levels tended to be related to the increasing infiltration levels of six types of immune cells (except for neutrophils in THYM)." (PMID 35751045, 2022). "The prognostic signature that we constructed consisted of seven cancer driver genes (CDKN2C, HRAS, IRAK1, LOX, MYCN, NRAS, and PABPC1)." (PMID 36017503, 2022). "Based on 10,080 samples, a pan-cancer analysis was also performed to determine the roles of CDKN2C in multiple cancers." (PMID 35751045, 2022). "Mutations in well-known cancer genes located on chromosome 1p, such as NRAS (1p13.2), GADD45A (1p31.2–31.1), CDKN2C (1p32.2), RAD45(1p32) and EPB41 (1p36.2–p34), have so far only sporadically been detected." (PMID 34385566, 2021). "Especially, cancer gene AKT2 (19q13.2) was amplified in two carcinomas, and CDKN2C (1p33) was homozygously deleted in other two cases." (PMID 25502777, 2014). "Especially, amplification of AKT2 was detected in two carcinomas and homozygous deletion of CDKN2C in other two cases." (PMID 25502777, 2014).
cancer (continued). "While Cdkn3 is expressed mostly in cancer, other CDKIs are categorized into the Cip/Kip family (p21 encoded by cdkn1a, p27/cdkn1b, and p57/cdkn1c) and INK4 family (p16/cdkn2a, p15/cdkn2b, p18/cdkn2c, and p19/cdkn2d)." (PMID 39668249, 2025). "Among the top three candidates for both gains and losses, CDKN2C gain, KIT loss, and GNAS loss were unique to GC cell lines, while ERBB3 gain, FBXW gain, and hypoxia-inducible factor 1a loss were also observed in other cancer types." (PMID 39461475, 2024). "Furthermore, on the basis of the first pan-cancer analysis of CDKN2C, the differential expression of CDKN2C and its prognostic significance were found in multiple cancers." (PMID 35751045, 2022). "Similar to SCLC, dysregulated CDKN2C expression was detected in 16 of the 20 cancers." (PMID 35751045, 2022). "CDKN2C has diverse expression patterns in different cancers." (PMID 35751045, 2022). "The different CDKN2C expression patterns in diverse cancers may imply the inconsistent role of CDKN2C expression in different cancers." (PMID 35751045, 2022). "The independent prognosis value of CDKN2C in eight cancers was detected." (PMID 35751045, 2022). "The comprehensive molecular mechanisms of the effects of CDKN2C expression on cancers remain unknown." (PMID 35751045, 2022). "The findings initially suggested that CDKN2C may participate in the development and progression of cancer via the immune microenvironment, although this must be verified by experiments." (PMID 35751045, 2022). "CDKN2C plays dual roles in the prognosis of various cancers." (PMID 35751045, 2022). "Furthermore, a pan-cancer analysis of CDKN2C expression and its clinical significance was performed to promote the understanding of the roles that CDKN2C plays in multiple cancers." (PMID 35751045, 2022). "As both CDKN2C and RB1 interact with G1/S cell cycle checkpoint through CDK4/6, they are potentially targetable through CDK4/6 inhibition, for which it has been shown in other cancers that co-deletion of CDKN2C and CDKN2A with functional presence of RB1 increases sensitivity in cell lines." (PMID 28427158, 2017). "The combined deletion of the p18 gene (CDKN2C) with the p16 gene is also found in human cancers." (PMID 23880895, 2013). "In addition to its prognostic effects, CDKN2C expression may be a marker for cancer identification and immunotherapy." (PMID 35751045, 2022). "However, we believe that the mechanisms of CDKN2C expression in cancer (including SCLC) transcend its role in these signaling pathways because our pan-cancer analysis revealed that upregulated CDKN2C expression demonstrated poor prognosis in most cancers, including SCLC." (PMID 35751045, 2022). "However, the CDKN2C expression diversity in cancers is still apparent." (PMID 35751045, 2022). "Besides, CDKN2C and ID2 are downregulated while IL6, BIRC3, PLAT, PPARG, and CEBPB are upregulated in three candidate TCM associated with Transcriptional misregulation in the cancer pathway." (PMID 34490085, 2021). "In pan-cancer analysis, SHOX2 expression positive correlated with CDKN2C (R = 0.41), COL6A1 (R = 0.35), COL6A2 (R = 0.37), DCHS1 (R = 0.37), MAPK7 (R = 0.34), PRRX1 (R = 0.37), RAB23 (R = 0.36) and RSRC1 (R = 0.36) via GEPIA2." (PMID 37170390, 2023). "In five cancers (KICH, etc.), a positive correlation between CDKN2C expression and HRD was observed (Spearman ρ > 0.3)." (PMID 35751045, 2022). "In a few cancers (particularly TCGT), CDKN2C expression was related to multiple immune-related genes, including TMEM173 (an immunostimulator), IL10RB (an immunoinhibitory), and TAPBP (a major histocompatibility complex molecule) in TGCT." (PMID 35751045, 2022). "Cyclin-dependent kinase inhibitors: The family of cyclin-dependent kinase inhibitor genes, CDKN2A (p16-INK4), CDKN2B (p15-INK4b), CDKN2C (p18-INK4c), and CDKN2D (p19-INK4d), are tumor suppressor genes generally inactivated in human cancers." (PMID 35056738, 2022).
cancer (continued). "Among the 32 cancers with TIMER data, CDKN2C expression represented weak to strong correlations with infiltration levels of all six types of immune cells in the top three cancers (i.e., all absolute values of Spearman ρ > 0.2, p < 0.05)—THYM, COAD, and HNSCC." (PMID 35751045, 2022). "The findings and correlation of CDKN2C expression with TMB, MSI, HRD, and the immune microenvironment suggest its potential usefulness as a biomarker in treating and differentiating cancers." (PMID 35751045, 2022). "This analysis validated the identification of genes that could be specific to cancer biology, such as IL7R, JUN, NR3C1 in Ba/Sq subtype, NPAS2, FOXQ1, GRHL3 in Luminal samples, or CDKN2C, FOXJ1, MEIS2, FGFR3 in both subtypes." (PMID 36944729, 2023). "The expression of CDKN2A, CDKN2B, CDKN2C, and CDKN2D was analyzed in 20 types of cancers." (PMID 35771229, 2022). "This study identified upregulated CDKN2C expression and its clinical significance in SCLC and other multiple cancers, suggesting its potential usefulness as a biomarker in treating and differentiating cancers." (PMID 35751045, 2022). "CDKN2C expression showed its clear clinical value in distinguishing several cancers (particularly SCLC) from controls, implying its potential usefulness in screening cancers." (PMID 35751045, 2022). "The expression of CDKN2A, CDKN2B, CDKN2C, and CDKN2D was positively correlated with the T stage, and the expression of CDKN2A, CDKN2B, and CDKN2C was positively correlated with the pathological stage, indicating that patients with more advanced cancer tended to express higher mRNA levels of INK4." (PMID 35771229, 2022). "Regarding hsa-miR-299::CDKN2C (top 479) and hsa-miR-301::BCL6 (top 593) in the 44 multi-cancer-related pairs, they are not listed in the ground-truth data." (PMID 28105958, 2016).
infection (3 papers, 2017 to 2025). The state of being infected such as from the introduction of a foreign agent such as serum, vaccine, antigenic substance or organism. "Cyclin-dependent kinase inhibitor 2C (CDKN2C) enforces cell cycle arrest in response to infection-related stress." (PMID 41333726, 2025). "Interestingly, overexpression of CDKN2C in HepAD38 increased infection of HepG2-NTCP acceptor cells by about threefold suggesting that the supernatant of CDKN2C-transduced HepAD38 cells has a higher infectivity." (PMID 32483149, 2020).
CDKN2C also shares sentences with these, for which no sentence is quoted: multiple myeloma (4 papers); cervical cancer (3); hyperparathyroidism (3); lymphoma (3); oligodendroglioma (3); pituitary tumor (3); acute myeloid leukemia (2); astrocytoma (2); head and neck cancer (2); leukaemia (2); meningioma (2); parathyroid adenoma (2); sarcoma (2); acute leukemia (1); acute lymphoblastic leukaemia (1); acute promyelocytic leukemia (1); adenoma (1); alcoholic liver diseases (1); Autoimmunity (1); B cell lymphoma (1); bladder cancer (1); carcinoid (1); cholangiocarcinoma (1); Cirrhosis (1); colon adenocarcinoma (1); digestive system cancer (1); dyslipidemia (1); endocervical adenocarcinoma (1); Epstein-Barr virus infection (1); esophageal carcinoma (1).
A further 41 diseases each share a sentence with CDKN2C in 1 paper.